CD27 (CD27 molecule)
Diseases named in the same sentence as CD27 in open-access papers (continued):
Sharing a sentence is not in itself a finding about the gene and the disease.
cancer (continued). "In our study, there was a significant increase in total and naive B lymphocytes and decrease of a B cell population defined as CD27‐IgD‐ double negative (DN) B cells in cancer survivors, which is inconsistent with the propensity of naive/memory B‐cell subsets observed in elderly." (PMID 33605556, 2021). "In the limited clinical trials to date, the CD27 agonizing monoclonal antibody, varlilumab, as monotherapy and with PD1/PDL1 checkpoint inhibitor therapy (nivolumab, atezolizumab), has resulted in varying degrees of objective clinical responses in a subset of cancer patients enrolled." (PMID 34630390, 2021). "Given that the expression of CD27 and CD28 are unchanged and the reduced functionality is true for the whole population, we do not believe that the reduction of functionality is due to a classical exhaustion process as the ones observed in chronic viral infections and cancer." (PMID 29176779, 2017). "Despite a CD4+ bias, there was no increase in CD4+ CD25+ CD27− FoxP3+ Tregs, which may have a negative effect on anti-cancer potency of adoptively transferred T cells." (PMID 28239467, 2017). "CD19 or CD27 antibody had a marginal effect in the Zfra-mediated cancer suppression, suggesting that CD19+ or CD27+ B cells are not involved in Zfra-mediated cancer suppression." (PMID 32764489, 2020). "In line with two inversely associated clusters of immune-based circulating biomarkers, we have previously shown a negative correlation between effector CD27− cytotoxic CD8+ T-cells and number of both CD33hi PMN-MDSCs and M-MDSC in pediatric cancer patients." (PMID 31799177, 2019). "The subset of CD8+CD45RA+CD27− effector cells was not the only subset with a higher rate of apoptosis and low ζ expression in CD8+ T cells of patients with cancer." (PMID 12610507, 2003).
hematologic malignancies (14 papers, 2019 to 2025). "In hematological malignancies, signaling through the CD27/CD70 axis stimulates cell survival, proliferation, and the acquisition of stemness properties in malignant cells, thereby contributing to disease progression." (PMID 40232798, 2025). "Varlilumab, as a CD27 agonistic antibody, has shown promising efficacy in hematological malignancies, particularly in combination approaches with PD1 axis-targeting ICIs, such as atezolizumab and nivolumab." (PMID 38136311, 2023). "Varlilumab (CDX-1127), a human IgG1 anti-CD27 agonist, has produced substantial and durable response in the phase I trial of patients with hematologic malignancies." (PMID 31186046, 2019). "In addition, mAbs against either CD70 or CD27 have been evaluated in hematological malignancies." (PMID 31186046, 2019). "Hematologic malignancies show activated Wnt, JAK/STAT, Hedgehog, and TGF-β pathways that maintain stemness, with CD27 crosslinking and CD70 reverse signaling further driving proliferation." (PMID 40896423, 2025). "Antigens such as CD27, CD37, CD70, CD80, CD86, B7-H3 and B7-H4, which are expressed in hematological malignancies and targeted by CAR-T cells, are promising candidates for clinical development." (PMID 38136311, 2023). "Due to the immune stimulatory potential, several CD27-targeting strategies, including agonistic mAbs and engineering intracellular domains in CAR-T cells, have been tested in preclinical models and clinical trials targeting solid or hematological malignancies." (PMID 39105866, 2024). "We also discuss the basic research and ongoing clinical trials on emerging immune checkpoints (Galectin-9/Tim-3, CD70/CD27, LAG-3, and LILRBs) and on new targets for CAR-T cell therapy (CD22, CD33, CD123, BCMA, CD38, and CD138) for the treatment of hematologic malignancies." (PMID 31186046, 2019). "In a healthy physiological setting, tightly controlled expression of both CD70 and CD27 plays a role in the co-stimulation of the immune response, but malignant cells co-expressing CD70 and CD27 promote stemness, proliferation, and survival of hematological malignancy." (PMID 39518937, 2024).
bacterial infection (5 papers, 2013 to 2023). "In advanced fibrosis, the CD27 + B cells are decreased in the peripheral blood, causing impaired cytokine and IgG production, vaccine hyperresponsiveness, and susceptibility to bacterial infection." (PMID 37885772, 2023). "Another interesting question concerns the memory function of γδ T cells during MCMV infection, as recently described for CD44+CD27− γδ T cells in mouse models of bacterial infections." (PMID 25747674, 2015). "Memory like NK expressing CD27 and KLRG1 developed in a bacterial infection model." (PMID 33370392, 2020). "CD27− γ9+δ2+ T cells were identified as functionally differentiated effector cells during M. tuberculosis infection suggesting that the CD27 negative γ9+ T cell population generated following CHDMAPP treatment is an appropriate phenotype for treating intracellular bacterial infection." (PMID 24098670, 2013).
infectious disease (3 papers, 2021 to 2023). A disorder directly resulting from the presence and activity of a microbial, viral, or parasitic agent in humans. "Therefore, it is surprising that CD27 deficiency predominantly predisposes for EBV-associated pathologies and not for susceptibilities to most other infectious diseases, and that CD27 or CD70 deficient patients still have some EBV-specific T-cell responses." (PMID 35053187, 2021).
kidney disease (2 papers, 2023 to 2024). "Though double labeling for CD27 and CD20 demonstrated a significant mature memory B cell population, whether these CD20+ CD27+ B cell-dominated structures represent a harmful or potentially beneficial occurrence for progression of renal diseases remains unclear." (PMID 37465675, 2023). "In contrast to kidney disease patients, the control group displayed a low relative frequency of CD27– and CD62L+ S-specific B-cell populations and high CD27+ S-specific B-cell fraction, indicating a more extensive germinal-center training of these S-specific B-cells." (PMID 38806532, 2024).
adenocarcinoma (1 paper, 2022). A common cancer characterized by the presence of malignant glandular cells. "To address this, we transplanted FoxP3.Luci-DTR + CD27 − / − mixed bone marrow chimeric mice subcutaneously with MC38 adenocarcinoma cells." (PMID 34423375, 2022).
cardiac disease (1 paper, 2014). "Linear regression analysis evidenced a positive trend for these cells as Chagas heart involvement increases (P = 0.0168), suggesting that the contraction of CD19+CD27+ cells occurs prior the onset of heart symptoms, and reverts as cardiac disease becomes more severe." (PMID 25111833, 2014).
intestinal diseases (1 paper, 2023). "Impaired regulation of cell death will disrupt the intestinal epithelial cell barrier and trigger a range of intestinal diseases, including CD27." (PMID 37550393, 2023).
respiratory disease (1 paper, 2025). "​Collectively, these findings connect CD27+ memory B cells to respiratory disease symptoms, supporting their procancer potential, though their exact mechanisms within the lung microenvironment require further study." (PMID 41377765, 2025).
CD27 also shares sentences with these, for which no sentence is quoted: multiple myeloma (13 papers); head and neck cancer (3); inflammatory bowel disease (3); kidney transplant (3); neurological disease (3); acute respiratory distress syndrome (2); alopecia areata (2); autoimmune hyperthyroidism (2); autoimmune thyroid disease (2); brain ischemia (2); chronic sinusitis (2); colorectal adenocarcinoma (2); diffuse malignant mesothelioma of (2); endometriosis (2); esophageal squamous cell carcinoma (2); GI tumors (2); hemophagocytic lymphohistiocytosis (2); idiopathic juvenile arthritis (2); mantle cell lymphoma (2); relapsing-remitting MS (2); T-cell lymphoma (2); ulcerative colitis (2); X-linked agammaglobulinemia (2); abortion (1); abscess (1); acute GVHD (1); Addison’s disease (1); Airway obstruction (1); Alcohol-Use Disorder (1); anaplastic large cell lymphoma (1).
A further 88 diseases each share a sentence with CD27 in 1 paper.